CPNE7 (copine 7)
Diseases named in the same sentence as CPNE7 in open-access papers:
CPNE7 is named in the same sentence as 23 diseases in open-access papers, as found by Europe PMC text mining. Sharing a sentence is not in itself a finding about the gene and the disease. The quoted sentences say what the papers report.
colorectal cancer (4 papers, 2019 to 2024). A primary or metastatic malignant neoplasm that affects the colon or rectum. "The aim of this study is to determine the contribution of CPNE7 to the growth, tumorigenesis, and invasion of colorectal cancer cells, and as a result of the analysis of the patient data, it was found that the expression of CPNE7 was associated with the metastasis of CRC." (PMID 38069026, 2023). "In this study, we have finally demonstrated that CPNE7 is associated with the initiation, progression, and metastasis of colorectal cancer, and through further studies in the future, we will be able to confirm its potential as a gene therapy or biomarker for colorectal cancer patients." (PMID 38069026, 2023). "We aimed to explore the biological function of CPNE7 and determine the impact of CPNE7 on chemotherapy resistance in colorectal cancer (CRC) patients." (PMID 38526029, 2024). "Research on CPNE7 in colorectal cancer with potential as a biomarker should be continuously conducted, and further verification in in vivo studies is also required." (PMID 38069026, 2023). "Schematic diagram of epithelial–mesenchymal transition pathways involving CPNE7 in colorectal cancer." (PMID 38069026, 2023). "When CPNE7 is over-expressed in colorectal cancer, the levels of epithelial markers decrease (purple) while mesenchymal markers increase (blue)." (PMID 38069026, 2023). "As the stage of the colorectal cancer increased, the expression of CPNE7 was found to be statistically significantly higher." (PMID 38069026, 2023). "As a result, CPNE7 expression was relatively higher in the colorectal cancer cell lines than in the normal cell line CCD-18-co, especially in SW480 and HCT116." (PMID 38069026, 2023). "Immunohistochemistry and quantitative polymerase chain reaction analysis the expression of CPNE7 in colorectal cancer." (PMID 37469397, 2023). "For the in vitro experiment, we first identified the basic CPNE7 protein expression in various wild-type colorectal cancer cell lines, including HCT116, HCT15, SW620, and DLD1." (PMID 37469397, 2023). "A CPNE7-siRNA-treated knockdown cell line generated a colorectal cancer cell line with relatively high CPNE7 expression compared to a normal cell line." (PMID 38069026, 2023). "This was confirmed at the mRNA and protein levels, showing that CPNE7 expression levels were reduced by more than 80% in all four colorectal cancer cell lines." (PMID 38069026, 2023). "In future studies, we will generate an antibody against CPNE7 to demonstrate its therapeutic potential targeting patients with CPNE7 overexpression in colorectal cancer." (PMID 38069026, 2023). "Interestingly, the interaction between CPNE7 and PKM2 may be what results in the phosphorylation of ERK, thereby accelerating colorectal cancer cell proliferation." (PMID 37469397, 2023). "To identify potential differentially expressed genes (DEGs) in colorectal cancer, we used the University of Alabama Cancer database to access The Cancer Genome Atlas (TCGA) and found that the mRNA level of CPNE7 is highly expressed in CRC tissue compared with adjacent normal tissue." (PMID 37469397, 2023). "However, it is necessary to identify the role of CPNE7 in other cancers as well as colorectal cancer, and the role of CPNE7 in CRC has not been clearly identified." (PMID 38069026, 2023).
oral squamous cell carcinoma (3 papers, 2021 to 2023). "Expression of UTP23, NUDT13 and CPNE7 are associated with poor prognosis in tumors including ovarian cancer, gastric cancer, oral squamous cell carcinoma." (PMID 36685828, 2022). "A recent study showed that high expression of CPNE7 in mesenchymal stromal cells (MSCs) promotes oral squamous cell carcinoma (OSCC) metastasis through the NF-κB pathway." (PMID 38069026, 2023). "However, a recent study showed that high expression of CPNE7 in mesenchymal stromal cells (MSCs) promotes oral squamous cell carcinoma (OSCC) metastasis through the NF-κB pathway." (PMID 38069026, 2023).
bladder cancer (2 papers, 2021 to 2023). "It is thought that mutation of CPNE7 may be related to an important mechanism related to bladder cancer." (PMID 38069026, 2023). "It is thought that mutation of CPNE7 may be associated with an important mechanism in bladder cancer." (PMID 38069026, 2023). "Sequencing analysis of bladder transitional cell carcinoma revealed 565 candidate gene mutations, including CPNE7 and serine/arginine repetitive matrix 5, suggesting that CPNE7 mutations may be related to important mechanisms involved in bladder cancer." (PMID 34367247, 2021). "Some studies have shown that CPNE7 is considered a potential tumor suppressor gene in bladder cancer." (PMID 38069026, 2023).
atherosclerosis (1 paper, 2019). A disease characterized by the build-up of fatty material and calcium deposition in the arterial wall resulting in partial or complete occlusion of the arterial lumen. "However, their involvement in atherosclerosis-related processes, such as cellular adhesion, neo-angiogenesis (DSG2, PSGs) and innate immunity (PSGs, CPNE7) suggests these proteins as potential atherosclerosis markers." (PMID 31242269, 2019).
breast carcinoma (1 paper, 2023). "And role of CPNE7 was tumor suppressor gene in breast cancer." (PMID 38069026, 2023). "CPNE7 is one of the tumor suppressor genes in breast cancer tissue." (PMID 38069026, 2023).
cervical squamous cell carcinoma (1 paper, 2021). A squamous cell carcinoma arising from the cervical epithelium. "Additionally, TCGA data showed that CPNE7 expression in primary tumours was significantly upregulated compared to that in normal tissues in Cervical squamous cell carcinoma (CESC) and Head and Neck squamous cell carcinoma (HNSC) (p ≤ 0.05) and could promote nodal metastasis." (PMID 34650058, 2021).
colon adenocarcinoma (1 paper, 2023). "Using Gene Expression Profiling Interactive Analysis, we discovered CPNE7 mRNA expression differences, in colon adenocarcinoma and rectal adenocarcinoma." (PMID 37469397, 2023).
colon cancer (1 paper, 2023). "This suggests that CPNE7 is involved in the regulation of colon cancer cell growth in vitro." (PMID 38069026, 2023).
colorectal tumors (1 paper, 2023). "Therefore, to confirm that CPNE7 increases the development of colorectal tumors, we constructed and packaged lentiviruses pLV19-CPNE7 and pLKO.1-shCPNE7." (PMID 37469397, 2023).
melanoma (1 paper, 2024). A malignant, usually aggressive tumor composed of atypical, neoplastic melanocytes. "For example, genes in cluster 2 (SPIRE2, SPATA2L), 3 (OCA2, DBNDD1, FANCA, GAS8) and 4 (URAHP, DEF8, CPNE7, MC1R) underlie the associations between melanoma and pigmentation traits." (PMID 38308491, 2024).
oral cancer (1 paper, 2024). "Previous studies have reported that CPNE7 functions as an oncogene in oral cancer and that its high expression can induce autophagy." (PMID 38526029, 2024).
oral disease (1 paper, 2020). "Our results suggest that the dual functions of CPNE7 and its peptide in tubular dentin formation and peritubular space occlusion are promising for oral disease-targeted application, especially those involving dentinal loss and pain." (PMID 33081300, 2020).
rectal adenocarcinoma (1 paper, 2023). "The Tumor Immune Estimation Resource revealed that CPNE7 is highly expressed in many tumor types, including colon and rectal adenocarcinoma." (PMID 37469397, 2023).
schizophrenia (1 paper, 2024). A major psychotic disorder characterized by abnormalities in the perception or expression of reality. "The remaining genes (G3bp2, Cpne7, Atcay, Zmat4, and Nxph1) of the unique LS genes are generally understudied in their role in regulating behavior, although Zmat4 is associated with schizophrenia." (PMID 38263132, 2024).
tumor (9 papers, 2021 to 2024). "We found that high expression of CPNE7 was associated with advanced T stage and with particular tumour sites." (PMID 38526029, 2024). "This research team identified a significant increase in expression in CRC patients and the role of the CPNE7 gene, a member of the copine family associated with tumor development." (PMID 38069026, 2023). "Increased expression of inflammatory cytokines causes subsequent expression of tumor-related genes such as various target genes and CPNE7." (PMID 38069026, 2023). "Taken together, these results revealed that CPNE7 truly exerts a pro‐tumour effect in CRC by preventing cell apoptosis." (PMID 38526029, 2024). "Since abnormal cell cycle progression and uncontrolled apoptosis tend to distinctly alter the proliferation and colony formation of tumour cells, we also subjected CPNE7‐knockdown CRC cells to cell cycle and apoptosis assays." (PMID 38526029, 2024). "We observed that CPNE7 was highly expressed in tumor tissues compared to normal tissues and its level was further upregulated in liver metastatic tissues, which was confirmed by qRT-PCR and IHC analysis." (PMID 39695095, 2024). "Transwell assay and wound-healing assay indicated that CPNE7 knockdown significantly reduced the migration potential of tumor cells." (PMID 39695095, 2024). "We also found that proliferative tumor cells were reduced by CPNE7 knockdown, supporting its therapeutic ability." (PMID 39695095, 2024). "Taken together, these results illuminate that CPNE7 overexpression promotes tumor cells growth in vivo." (PMID 39695095, 2024). "Then, Western blot analysis confirmed reduced CPNE7 expression in the CPNE7 knockdown groups, which corresponded to the observed inhibition of tumor growth in these xenografts." (PMID 39695095, 2024). "Based on an analysis of The Cancer Genome Atlas database, Tumor Immune Estimation Resource and Gene Expression Profiling Interactive Analysis, we explored the expression of CPNE7 in tumors." (PMID 37469397, 2023). "CPNE7 is a transcription factor that promotes tumor invasion and metastasis by inducing EMT in CRC cell lines but also plays a dual role in suppressing it depending on the situation." (PMID 38069026, 2023). "IHC staining of CRC patient tumor samples further validated that CPNE7 in CRC tissue was significantly higher than that in normal tissue." (PMID 37469397, 2023). "CPNE7, a calcium-dependent phospholipid-binding protein, mediates signal transduction and metastasis in many tumours." (PMID 34650058, 2021). "According to the data of RNA- sequencing analysis, CPNE7 in MSCs (the upregulated differential gene) was predicted as a potential regulator of the NF-κB pathway to promote the metastasis of tumour cells." (PMID 34650058, 2021). "Our results on the CPNE7 expression level were partly confirmed by tumour tissue data from the TCGA database (in comparisons between para- and tumour tissues)." (PMID 34650058, 2021). "Besides, transwell and wound-healing assays showed that CPNE7 overexpression resulted in increased migration of tumor cells." (PMID 39695095, 2024). "Therefore, it was confirmed that CPNE7 expression affects tumor progression, metastasis, and survival." (PMID 38069026, 2023). "Our results showed that CPNE7 acts as a tumor oncogene in CRC cells in vitro." (PMID 38069026, 2023). "The implications of this high expression of CPNE7 could possibly affect tumor progression and patient survival." (PMID 38069026, 2023). "Additionally, we found that CPNE7 knockdown also increased the apoptotic ratio of tumor cells." (PMID 39695095, 2024). "Importantly, a recent study indicates CPNE7 may be a tumor driver." (PMID 39695095, 2024). "CPNE7 was highly expressed in CRC tissues, and its expression was correlated with T stage and tumour site." (PMID 38526029, 2024).
tumor (continued). "Previous studies have shown that ATG9B not only regulates cellular autophagy, but is also is correlated with tumour drug resistance, therefore, we selected ATG9B as a potential downstream molecule of CPNE7." (PMID 38526029, 2024). "Some CSC marker genes showed extremely disparate expression levels between normal and tumor samples, such as PLCG2, DDX11, IER5L, LENG8, HAGHL and CPNE7." (PMID 37377935, 2023). "Our research verified that CPNE7 plays a key role in CRC progression, especially in tumor proliferation and invasion." (PMID 37469397, 2023). "Analyzing the clinicopathological characteristics, we observed that CPNE7 upregulates in CRC and is related to tumor extension." (PMID 37469397, 2023). "In addition, knockdown of CPNE7 significantly inhibited cell proliferation in BALB/c nude mice and enhanced sensitivity to 5‐fluorouracil treatment, as indicated by both tumour volume and weight." (PMID 38526029, 2024). "We found a significant correlation with high expression of CPNE7 and tumor extension, but not with age, gender, TNM stage, differentiation, distant metastasis, or lymph node involvement." (PMID 37469397, 2023). "According to the expression levels and regression coefficients, the downregulated BAX, PWP2, SERTAD1, S1PR4, ZFAND1, NUDT13 and ZNF107 with HR < 1 were considered as tumor suppressors, whereas the MVD, BAD, CPNE7, CPNE7, UTP23 and ZNF124 upregulated with HR > 1 were regarded as oncogenes." (PMID 36685828, 2022). "Moreover, we analyzed the correlation among four-gene signature (FeSig) (BID, TAZ, MT1G, and SLC7A11), downstream hub genes (CPNE7, WNT10B, ADAMTS14, and RUFY4), and immune checkpoints (PD-1, CTLA4, LAG3, and TIGIT) to further discover potential molecular mechanisms of tumor immunity." (PMID 34367965, 2021). "Notably, delivery of CPNE7 shRNA or the small molecule gramicidin, which blocks the interaction between CPNE7 and NONO, hinders tumor growth in vivo." (PMID 39695095, 2024).
cancer (6 papers, 2019 to 2024). A tumor composed of atypical neoplastic, often pleomorphic cells that invade other tissues. "Upregulation of CPNE7 promotes proliferation and metastasis of cancer cells in vitro and in vivo, and vice versa." (PMID 39695095, 2024). "Currently, the role of CPNE7 in cancer mechanisms is not well understood, and further research is needed." (PMID 38069026, 2023). "At present, the role of CPNE7 in cancer mechanisms is not clearly known, and therefore, further research is needed." (PMID 38069026, 2023). "The role of CPNE7 in promoting or inhibiting CRC in cancer pathogenesis is currently unclear and requires further investigation." (PMID 38069026, 2023). "Comparing and analyzing transcriptome sequencing between exogenous up-/downregulated CPNE7 CRC cells and the controls, we found that CPNE7 activates mitogen-activated protein kinase (MAPK) signaling pathway stimulating cancer cell proliferation." (PMID 37469397, 2023). "Given the high expression of CPNE7 found in public transcriptome sequencing data, we suggest that it may have a cancer‐promoting effect." (PMID 38526029, 2024). "We observed CPNE7 was also distributed in the nucleus of cancer cells, implying it may regulate ZFP42 transcription." (PMID 39695095, 2024). "In addition, it will prove its potential as a marker for predicting progression in CRC patients and analyze the functional effect of CPNE7 in mediated hallmarks of cancer, including cell proliferation, migration, and invasion." (PMID 38069026, 2023). "In addition, it will prove its potential as a prognositc marker in CRC patients and analyze the functional effect of CPNE7 in mediated hallmarks of cancer, including cell proliferation, migration, and invasion." (PMID 38069026, 2023). "Decreasing the expression of CPNE7 in CRC significantly mitigates cancer cell functions." (PMID 38069026, 2023). "Analysis of the mechanism by which CPNE7 accelerates cancer cell proliferation uncovered that CPNE7 could promote AKT and ERK phosphorylation." (PMID 37469397, 2023). "The upregulation of CPNE7 in CRC might contribute to the EMT process of cancer cells." (PMID 38069026, 2023). "In summary, our study showed that CPNE7 is over-expressed in CRC tissues and promotes cancer cell proliferation." (PMID 37469397, 2023). "If we can find the precise site where CPNE7 phosphorylates in the MAPK pathway, perhaps CPNE7 could be applied to clinical practice as a biomarker or anti-cancer target." (PMID 37469397, 2023). "However, the rest of the genes (LGI1, PCSK2, CTNND2, SLC6A19, DAO, TMEM82 and CPNE7) could be related to CRC and have been previously identified in other types of cancer." (PMID 30940089, 2019). "We also pointed out that NONO cooperated with CPNE7 to promote ZFP42 transcription and cancer growth and metastasis, which clearly defined its functional mechanism." (PMID 39695095, 2024). "We observed CPNE7 and NONO were colocalized in the nucleus of cancer cells, implying they may jointly regulate the transcription of ZFP42." (PMID 39695095, 2024).
infection (2 papers, 2023 to 2024). The state of being infected such as from the introduction of a foreign agent such as serum, vaccine, antigenic substance or organism. "mRAN and protein expression levels were decreased after CPNE7 shRNA infection, and the cell number in the migration and invasion assay decreased compared to the control." (PMID 38069026, 2023). "We generated HCT116 cells with stable knockdown of CPNE7 via lentiviral infection." (PMID 38526029, 2024). "Next, CPNE7 shRNA infection was performed to make a stable knockdown cell line for in vivo studies." (PMID 38069026, 2023). "Given that inhibition of CPNE7 by siRNA treatment and shRNA infection had an inhibitory effect on CRC cell motility, we sought to identify the signaling pathway of CPNE7." (PMID 38069026, 2023).
genetic disorder (1 paper, 2024). "Hutchinson‐Gilford progeria syndrome is a well‐documented genetic disorder demonstrating dramatically accelerated aging of major organs and tissues of the body including teeth, which exhibit similar characteristics to those of Cpne7−/− mouse." (PMID 38105557, 2024).
neurodegenerative disease (1 paper, 2021). A disorder of the central nervous system characterized by gradual and progressive loss of neural tissue and neurologic function. "On the top of its CPNE7’s potential application in dentin regeneration and dental pulp protection, this possibility suggests that CPNE7-induced autophagy may be a potential therapeutic material for neurodegenerative diseases." (PMID 33981704, 2021).
CPNE7 also shares sentences with these, for which no sentence is quoted: bladder transitional cell carcinoma (1 paper); gastric cancer (1); head and neck squamous cell carcinoma (1); ovarian carcinoma (1).